BLNK (B cell linker)
Description:
Functions as a central linker protein, downstream of the B-cell receptor (BCR), bridging the SYK kinase to a multitude of signaling pathways and regulating biological outcomes of B-cell function and development. Plays a role in the activation of ERK/EPHB2, MAP kinase p38 and JNK. Modulates AP1 activation. Important for the activation of NF-kappa-B and NFAT. Plays an important role in BCR-mediated PLCG1 and PLCG2 activation and Ca(2+) mobilization and is required for trafficking of the BCR to late endosomes. However, does not seem to be required for pre-BCR-mediated activation of MAP kinase and phosphatidyl-inositol 3 (PI3) kinase signaling. May be required for the RAC1-JNK pathway. Plays a critical role in orchestrating the pro-B cell to pre-B cell transition. May play an important role in BCR-induced B-cell apoptosis.
Synonyms: SLP-65; BASH; SLP65; Ly57; BLNK-s; bca; AGM4
Tractability: Antibody: UniProt places it where antibodies can reach, with high confidence; its Gene Ontology location is reachable by antibodies, with high confidence; the Human Protein Atlas places it where antibodies can reach. PROTAC: its protein half-life has been measured.
Gene: Protein-coding gene on chromosome 10 (96,189,171 to 96,272,658, reverse strand). Ensembl gene ENSG00000095585.
Subcellular location: Cytoplasm; Cell membrane
Subcellular location (Human Protein Atlas): Plasma membrane; Vesicles
Pathways (Reactome):
Immune System: Antigen activates B Cell Receptor (BCR) leading to generation of second messengers; Regulation of signaling by CBL
Disease: Potential therapeutics for SARS
Gene Ontology:
Molecular function: enzyme binding; lipid binding; molecular condensate scaffold activity; phospholipase binding; protein binding; protein kinase binding; protein tyrosine kinase binding; SH2 domain binding; signaling adaptor activity; transmembrane receptor protein tyrosine kinase adaptor activity
Biological process: B cell receptor signaling pathway; intracellular signal transduction; B cell differentiation; cell surface receptor protein tyrosine kinase signaling pathway; humoral immune response; inflammatory response; positive regulation of gene expression
Cellular component: cytosol; membrane; plasma membrane; cytoplasm
Genetic constraint (gnomAD): Loss-of-function variants: 26 observed, 69.81 expected, observed/expected ratio (o/e) 0.37, 90% interval 0.27 to 0.52. The upper end of that interval is the gene's LOEUF score, 0.52, which puts it in group 2 of 6, group 1 being the genes least tolerant of losing a copy. Missense variants: 441 observed, 563.24 expected, observed/expected ratio (o/e) 0.78, 90% interval 0.72 to 0.85. Synonymous variants: 170 observed, 203.49 expected, observed/expected ratio (o/e) 0.84, 90% interval 0.74 to 0.95.
Gene-disease validity (ClinGen):
ClinGen rates the evidence that BLNK causes each of these diseases.
agammaglobulinemia 4, autosomal recessive (autosomal recessive): Definitive.
Homologues: Orthologues: chimpanzee BLNK (99% identical), macaque BLNK (96% identical), pig BLNK (91% identical), dog BLNK (88% identical), mouse Blnk (86% identical), rat Blnk (83% identical), guinea pig BLNK (67% identical), rabbit BLNK (54% identical), tropical clawed frog blnk (44% identical), zebrafish blnk (37% identical), zebrafish si:dkeyp-117b11.1 (23% identical). Paralogues in human: LCP2 (24% identical), SH2D6 (20% identical), CLNK (17% identical).
Diseases named in the same sentence as BLNK in open-access papers:
BLNK is named in the same sentence as 50 diseases in open-access papers, as found by Europe PMC text mining. Sharing a sentence is not in itself a finding about the gene and the disease. The quoted sentences say what the papers report.
agammaglobulinemia (9 papers, 2018 to 2025). A decreased level of serum immunoglobulins. "It has been reported that agammaglobulinemia patients have BLNK mutations that contribute to defects in mature B cell development." (PMID 38521787, 2024). "This male case of agammaglobulinemia highlights the necessity of considering BLNK mutations in children with B cell deficiency, even though they are known to be rare causes of agammaglobulinemia." (PMID 35719418, 2022). "Bruton’s agammaglobulinemia was associated with classic BTK mutations like c.1483G>A, whereas functional B-cell deficiency was connected to BLNK, indicating issues in early B-cell development." (PMID 40806973, 2025). "A similar clinical phenotype of agammaglobulinemia or hypogammaglobulinemia is observed in patients with hemizygous variants in BTK, biallelic variants in BLNK, heterozygous gain-of-function (GOF) PIK3CD, or loss-of-function (LOF) PIK3R1 variants, which all encode proteins involved in BCR signaling." (PMID 41607487, 2025). "Although XLA is the most common form of agammaglobulinemia, several other congenital agammaglobulinemias have been identified that are inherited in an autosomal dominant or recessive manner (μ chain, Igα, Igβ, λ5, E47, BLNK, PIK3R1)." (PMID 36359748, 2022). "Agammaglobulinemia with other inherited pattern were also concluded: AR agammaglobulinemia was associated with mutations in several other genes such as IGHM, IGLL1, CD79A, CD79B, BLNK, PIK3R1, and TCF3 genes; AD-related agammaglobulinemia was also found with LRRC8A and TCF3 gene mutations." (PMID 36140582, 2022). "Mutations within the BCR signalosome such as BTK or BLNK usually result in absent protein expression, a severe block of BCR signaling and an arrest at the pre-B cell stage, subsequently leading to agammaglobulinemia." (PMID 30619340, 2018).
Alzheimer disease (3 papers, 2021 to 2024). A progressive, neurodegenerative disease characterized by loss of function and death of nerve cells in several areas of the brain leading to loss of cognitive function such as memory and language. "In contrast, the most significant finding for granulocytes was linked to the BLNK (P = 3.35 × 10–9, q = 0.069), a gene involved in kinase signaling and previously associated with Alzheimer disease." (PMID 38778395, 2024). "Beyond the field of oncology, BLNK may also promote chondrocyte injury, contributing to osteoarthritis, and be associated with the microglia response to amyloid-β, a pathological change of Alzheimer’s disease." (PMID 37744379, 2023). "BLNK assists in activation of immune cells, APOE codes for apolipoprotein associated with Alzheimer’s disease and IRF1 is activated by interferon gamma and regulates expression of antiviral genes." (PMID 34681730, 2021).
B cell deficiency (3 papers, 2022 to 2025). A broad classification of disorders where circulating numbers of B lymphocytes are decreased or ineffective. "We propose that the persistent B-cell deficiency linked to the BLNK mutation can explain her clinical phenotype." (PMID 36465938, 2022). "Autosomal dominant mutations in BLNK were associated with functional B-cell deficiency." (PMID 40806973, 2025).
leukemia (3 papers, 2022 to 2023). A malignant (clonal) hematologic disorder, involving hematopoietic stem cells and characterized by the presence of primitive or atypical myeloid or lymphoid cells in the bone marrow and the blood. "We present the case of a female patient with a heterozygous somatic BLNK mutation, a T-cell LGL (large granular lymphocyte) leukemia, and multiple autoimmune diseases." (PMID 36465938, 2022). "As a potential tumor suppressor, BLNK is widely studied and considered a biomarker in leukemia." (PMID 37744379, 2023). "ELN-PAX5 interaction results in the decreased expression of LEF1, MB1, and BLNK, while PML-PAX5 is critical in the early stages of leukemia." (PMID 37335685, 2023).
lymphoma (3 papers, 2022 to 2024). A malignant (clonal) proliferation of B- lymphocytes or T- lymphocytes which involves the lymph nodes, bone marrow and/or extranodal sites. "In summary, in human lymphoma cells LUX and IB have quite distinct mechanistic effects on the phosphorylation of BTK and its activity, and on the upstream kinases SYK and LYN, and the adaptor protein BLNK against which LUX is very potent and IB had little effect." (PMID 36888611, 2023).
acute lymphoblastic leukemia (2 papers, 2022 to 2025). Leukemia with an acute onset, characterized by the presence of lymphoblasts in the bone marrow and the peripheral blood. "Downregulation/mutation in the BLNK gene has been shown to induce acute lymphoblastic leukemia through JAK3 signaling." (PMID 35629968, 2022). "For instance, in our previous study of B‐cell acute lymphoblastic leukemia (B‐ALL), B‐cell linker (BLNK) molecule (also known as SLP‐65 or BASH), a cytoplasmic adaptor protein involved in B‐cell receptor signaling, was investigated." (PMID 40325913, 2025).
breast carcinoma (2 papers, 2021 to 2022). "We found that in a cohort of 398 patients with ErbB2/Her2-positive breast carcinoma, increased BLNK mRNA expression is significantly associated with increased disease-free survival: p-value = 0.0018, hazard ratio = 0.6 (95% CI 0.43–0.83)." (PMID 35933456, 2022). "Since BLNK blocks breast cancer cell tumorigenicity, it is conceivable that increased BLNK gene expression in patients’ tumors is associated with slower breast cancer progression." (PMID 35933456, 2022). "We found that increased BLNK mRNA expression is significantly associated with increased disease-free survival of patients with ErbB2/Her2-positive breast carcinoma." (PMID 35933456, 2022). "We show here that ErbB2-dependent IRF6 downregulation reduces cellular levels of the pro-apoptotic protein BLNK and that BLNK loss blocks anoikis of breast cancer cells and promotes their tumorigenicity in vivo." (PMID 35933456, 2022). "Thus, proteasome inhibition represents potential novel pharmacological approach for causing BLNK-dependent breast cancer cell anoikis." (PMID 35933456, 2022). "Thus, our data are consistent with a model whereby ErbB2-dependent ERK activation downregulates IRF6, IRF6 downregulation causes reduction in the cellular BLNK levels, whereas BLNK loss in turn inactivates p38MAPK and thus blocks breast cancer cell anoikis." (PMID 35933456, 2022). "We also observed that a small molecule proteasome inhibitor bortezomib used for multiple myeloma treatment upregulates IRF6 and BLNK in detached ErbB2-positive breast cancer cells and kills them in a BLNK-dependent manner." (PMID 35933456, 2022). "Our data indicate that proteasome inhibition represents a potential pharmacological approach for upregulating BLNK in breast cancer cells." (PMID 35933456, 2022). "In an effort to further demonstrate that BLNK triggers apoptosis of detached breast cancer cells we established that BLNK triggers the cleavage (a sign of activation) of procaspsase-3, the key apoptosis executioner." (PMID 35933456, 2022). "In summary, ErbB2-induced BLNK downregulation in detached breast cancer cells is driven by IRF6 downregulation." (PMID 35933456, 2022). "Another possible application of our finings is to use BLNK as a predictive marker in ErbB2-positive breast cancer." (PMID 35933456, 2022). "Furthermore, we used publicly available data on mRNA levels in multiple breast cancers to demonstrate that increased BLNK mRNA levels correlate with increased relapse-free survival in a cohort of approximately 400 patients with ErbB2-positive breast cancer." (PMID 35933456, 2022). "We further tested whether understanding of the mechanisms by which ErbB2 downregulates BLNK can potentially be used for designing anoikis-promoting breast cancer treatments." (PMID 35933456, 2022). "In search for pharmacological approaches allowing to upregulate BLNK in tumor cells we found that clinically approved proteasome inhibitor bortezomib upregulates IRF6 and BLNK in human breast cancer cells and inhibits their 3D growth in a BLNK-dependent manner." (PMID 35933456, 2022). "To examine the role of BLNK in the regulation of anoikis of ErbB2-overproducing breast cancer cells by a complementary approach, we generated a variant of MCF-ErbB2 cells MCF-ErbB2-BLNK in which exogenous BLNK expression is controlled by the doxycycline-inducible promoter." (PMID 35933456, 2022). "Indeed, we observed that a small molecule proteasome inhibitor bortezomib used for multiple myeloma treatment upregulates both IRF6 and its target BLNK in ErbB2-positive breast cancer cells BT474." (PMID 35933456, 2022). "Moreover, we established that BLNK promotes anoikis by activating p38 MAP kinase and that ErbB2-dependent BLNK downregulation blocks breast cancer cell anoikis." (PMID 35933456, 2022). "In addition, we found that BLNK upregulation in human ErbB2-positive breast cancer cells blocks their ability to form tumors in mice." (PMID 35933456, 2022).
breast carcinoma (continued). "Thus, we tested whether BLNK upregulation blocks the ability of ErbB2-positive breast cancer cells to form tumors in mice." (PMID 35933456, 2022). "Thus, ErbB2 downregulates BLNK in detached breast cancer cells." (PMID 35933456, 2022). "Moreover, novel proteasome inhibitors are now being developed for solid tumor treatment and could be explored as BLNK-upregulating drugs in ErbB2-positive breast cancer." (PMID 35933456, 2022). "Hence, BLNK upregulation blocks tumorigenicity of ErbB2-positive breast cancer cells in vivo." (PMID 35933456, 2022). "We found that ErbB2 promotes survival of breast cancer cell detached from the ECM by a novel mechanism involving downregulation of transcription factor IRF6 and further downregulation of the cell death-promoting protein BLNK." (PMID 35933456, 2022). "We further observed that trastuzumab, a therapeutic anti-ErbB2 antibody, upregulates BLNK in human trastuzumab-sensitive but not trastuzumab-resistant ErbB2-positive breast cancer cells." (PMID 35933456, 2022).
breast tumor (2 papers, 2022 to 2024). "In summary, we have discovered a novel mechanism of ErbB2-driven breast tumor growth driven by ErbB2-dependent BLNK downregulation." (PMID 35933456, 2022). "In summary, we discovered a novel mechanism of ErbB2-driven 3D breast tumor growth mediated by ErbB2-dependent BLNK downregulation." (PMID 35933456, 2022). "We found that BLNK upregulation in breast tumor cells by a genetic approach blocks their tumorigenicity." (PMID 35933456, 2022). "Additionally, another study demonstrated that ErbB2 inhibits the upregulation of BLNK by reducing the levels of the tumor cell transcription factor IRF6, thus facilitating breast tumor growth." (PMID 39596658, 2024).
Burkitt lymphoma (2 papers, 2018 to 2021). A rare form of malignant mature B-cell non-Hodgkin lymphoma. "To test the importance of these adaptors, we used pull‐down assays to analyze interactions of endophilin A2‐GFP with the BCR in DG75 Burkitt lymphoma cells in the context of GRB2 or BLNK deletion." (PMID 34323351, 2021).
colorectal cancer (2 papers, 2022 to 2025). A primary or metastatic malignant neoplasm that affects the colon or rectum. "BLNK is an adaptor protein of the B-cell receptor signaling pathway and has been identified as an independent risk factor for colorectal cancer recurrence as well as a positive regulator of Met signaling in non-small cell lung cancer." (PMID 40050982, 2025).
immunodeficiencies (2 papers, 2019 to 2023). "Genetically defined immunodeficiencies were first described with the identification of BTK mutations in X-linked (Bruton’s) agammaglobulinemia, and subsequently expanded to include several B-cell receptor genes, including BLNK, μ heavy chain, and CD79A/B5,38." (PMID 31409799, 2019).
non-small cell lung carcinoma (2 papers, 2024 to 2025). A group of at least three distinct histological types of lung cancer, including non-small cell squamous cell carcinoma, adenocarcinoma, and large cell carcinoma. "An experimental study has suggested that BLNK were up-regulated in Waldenström’s macroglobulinemia but not in MM, and it contributed to the regulation of Met receptor signaling in non-small cell lung cancer." (PMID 38280104, 2024).
alcoholism (1 paper, 2017). "While many identified genes were generally in alignment with prior knowledge, further work should be done to understand the associations between alcoholism and the five genes that went uncorroborated in the literature (BLNK, BMPER, PDLIM5, VEPH1, AMPD3)." (PMID 28361705, 2017).
anaplastic cancer (1 paper, 2025). "Regarding the downregulated genes in ATC, three of them, namely PRKCD, CYFIP2, and BLNK, were described to have tumor suppressor activity and their downregulation is in line with the more aggressive behavior that characterizes an anaplastic cancer." (PMID 40965626, 2025).
Autoimmunity (1 paper, 2020). The occurrence of an immune reaction against the organism's own cells or tissues. "Other PID have leaky B cell development with alterations of the B cell diversity autoimmunity and B cell malignancies, jointly termed common variable immunodeficiency (CVID) and include PID with mutations in BAFF and the BAFF receptor TACI, BLNK/SLP65 (mouse) and ICOS (expressed on Tfh cells)." (PMID 33240268, 2020).
bladder cancer (1 paper, 2017). "For example, in the TCGA bladder cancer (BLCA) dataset, BLK and CD19 show nearly perfect marker-like co-expression, while the putative B-cell marker BLNK is largely uncorrelated with CD19." (PMID 28239471, 2017).
Colon cancer (1 paper, 2018).
COVID-19 (1 paper, 2023). A disease caused by infection with severe acute respiratory syndrome coronavirus 2. "In contrast to COVID-19(+) TV, highly expressed in the COVID-19(-) PU control group included MHC class II antigen processing (HLA-DRB3/4, HLA-DPB1, HLA-DRA, CIITA, and CD74), mast cell degranulation (TPSAB1/B2), B cell activation (CXCL13, BLNK, IL-6) and histone modification (USP21, HIST1H4E)." (PMID 37026002, 2023).
emphysema (1 paper, 2023). "Therefore, the upregulation of BLNK and IL1R1 may be associated with airway inflammation rather than emphysema formation." (PMID 38203236, 2023). "Regarding the upregulated DEGs in COPD, CD109, B cell linker (BLNK), interleukin-1 receptor type 1 (IL1R1), CD1A, and carboxypeptidase A3 (CPA3) are related to T-helper cell type 2 (Th2) inflammation, but not to emphysema formation." (PMID 38203236, 2023).
kidney damage (1 paper, 2023). "The BLNK, MS4A4A, and COL15A1 were all negatively correlated with eGFR, indicating that these genes may aggravate kidney damage in patients with DN." (PMID 36765416, 2023).
lung carcinoma (1 paper, 2021). "Strong upregulation of BLNK mRNA by treatment with A + N or camptothecin was also observed in NCI-H460 lung cancer cell line, what indicates that activation of the gene by stress is not a peculiarity of A549 cells." (PMID 34681730, 2021). "The appearance of BLNK protein in A549 lung cancer cells exposed to A + N was very surprising, because the expression of BLNK gene is limited to B cells, plasmacytoid dendritic cells and microglial cells." (PMID 34681730, 2021). "Our observations indicate that, for some reason, function of BLNK protein is required in lung cancer cells in stress conditions elicited by treatment with A + N." (PMID 34681730, 2021). "Unexpectedly, we found that in A549 lung cancer cell line the drug combination A + N induced the expression of several elements of a signaling pathway encompassing TREM2 (a receptor), TYROBP (a co-receptor), SYK (a kinase) and BLNK (an adaptor protein)." (PMID 34681730, 2021).
lymph node metastasis (1 paper, 2015). "Correlation was shown between PD-L1 and tumor size and lymph node metastasis, HOXB9 and tumor size, BLNK and perineural invasion, and between ZNF813 and perineural invasion." (PMID 26041877, 2015).